CCL2 (C-C motif chemokine ligand 2)
Diseases named in the same sentence as CCL2 in open-access papers (continued):
Sharing a sentence is not in itself a finding about the gene and the disease.
Obesity (continued). "However, cytokines induced by ME in breast carcinoma cells themselves, notably CCL2—a key chemokine mediating macrophage recruitment in obesity-associated breast tumors —may also play a role in driving this stromal activation." (PMID 40868123, 2025). "Similarly, miR-126 had altered expression in obesity and may modulate CCL2 (chemokine ligand 2) through genes that encode ETS1, MAX, NFKB1, RELB, and STAT6 proteins." (PMID 36355127, 2022). "Also, Sinya and colleagues showed that CCL2 deficiency decreased adipose tissue MΦ proliferation in vivo, and the in situ proliferation of resident MΦs driven by CCL2 is a crucial process for MΦ accumulation in adipose tissue in obesity." (PMID 26155942, 2015). "The adipocyte is a major source of CCL2 in obesity, the production of which is triggered when cells are exposed to inflammatory cytokines and fatty acids, and recently, microRNAs 126 and 193b have also been implicated in the regulation of CCL2 secretion in obese adipose tissue." (PMID 23557387, 2013). "In obesity and diabetes, its inflammatory transformation results in increased secretion of leptin, resistin, and MCP-1/CCL2, along with diminished adiponectin secretion." (PMID 41596265, 2026). "The human data shows that obesity enhances the activation of the FA/HIF‐1α/CCL2 pathway in tumor tissue and the CCL2/CCR2/PPARα axis in adjacent adipose tissue, thereby accelerating tumor progression and promoting adipolysis in the surrounding adipose tissue." (PMID 41160815, 2026). "Principal component analysis (PCA) revealed two dominant components separating metabolic (irisin, HOMA-IR, insulin, BMI) and inflammatory (IL-1β, CCL2) profiles, supporting the distinction between metabolic and inflammatory pathways in obesity." (PMID 42196825, 2026). "Among the obesity groups, significant differences in Ccl2 and Tgfb1 expression were found between the HFD-30:1 and HFD-5:1 groups." (PMID 40573106, 2025). "CCL2 mediates monocyte recruitment, M1 polarization and the upregulation of TNF-α and IL-6 in fat pads, contributing to the inflammatory milieu linked to obesity-associated comorbidities." (PMID 40328980, 2025). "Diallyl disulfide can suppress the accumulation/activation of macrophages in adipose tissue and inhibit the release of CCL2 from adipocytes lowering the inflammatory status induced by obesity." (PMID 40076892, 2025). "This suggests that leptin contributes to the inflammatory milieu in obesity by upregulating CCL2, which in turn facilitates macrophage infiltration into WAT." (PMID 40518865, 2025). "Several studies have demonstrated that Ccl2 is upregulated in AT from both humans and mice with obesity." (PMID 40847538, 2025). "Monocyte chemoattractant protein-1 (MCP-1), also referred to as C-C motif ligand 2 (CCL2) has been involved in the pathogenesis of obesity, MASLD, and atherosclerosis." (PMID 40794228, 2025). "We observed an increase in the expression of genes encoding CCL2, LEP, and the demethylase KDM6B in vWAT of patients with class II to III obesity, compared to the normal weight/overweight group." (PMID 40518865, 2025). "Our findings show that obesity enhances CCL2 expression in ASCs, alongside increased expression of H3K27 modifiers, key epigenetic regulators linked to gene activation in WAT stromal cells." (PMID 40518865, 2025). "Under ME conditions in vitro, we detected in BC cells significantly increased expression of TNFα, CCL2, IL-6 and human IL-8, well-known TLR-controlled cytokines, tightly implicated in breast tumorigenesis and the obesity-cancer link." (PMID 40868123, 2025). "We further confirmed CCL2 production from MSCs in response to clinically relevant samples from patients with obesity, or healthy controls." (PMID 40770765, 2025). "Elevated CCL4 and CCL2 expression were observed in subcutaneous adipose tissue cells isolated from patients with obesity compared with those in patients with normal body weight." (PMID 40145019, 2025).
Obesity (continued). "To investigate, we assessed the direct effect of leptin on H3K27 modifiers and CCL2 secretion by ASCs, simulating the leptin‐rich environment of obesity in vitro." (PMID 40518865, 2025). "Several studies performed in humans have indicated that CCL2 levels are increased in both diabetes and obesity." (PMID 39457105, 2024). "Circulating leptin in obesity enhances adipocyte and systemic inflammation, up-regulating monocyte chemoattractant protein-1 (MCP-1), also known as CCL2." (PMID 39585028, 2024). "CCL2 (C-C Motif Chemokine Ligand 2) was down-regulated in the ICU patients as was CX3CR1 (C-X3-C Motif Chemokine Receptor 1), which is associated with obesity, a risk factor for severe influenza disease." (PMID 39192977, 2024). "VAT metaflammation in obesity, as measured by mRNA levels of TNF-α, IL6, and MCP-1/CCL2, is associated with insulin resistance and cellular senescence." (PMID 39063184, 2024). "Collectively, these results suggested that obesity facilitates KLF7/CCL2 expression of BMA in the bone marrow cavity." (PMID 38221626, 2024). "This review provides an in-depth analysis of specific chemokines involved in the development of obesity, including C-C motif chemokine ligand 2 (CCL2), CCL3, CCL5, CCL7, C-X-C motif chemokine ligand 8 (CXCL8), CXCL9, CXCL10, CXCL14, and XCL1 (lymphotactin)." (PMID 39334887, 2024). "In obesity-induced type 2 diabetes, pro-inflammatory molecules like IL-1β, IL-6, CCL2, CCL5, and leptin play key roles in the accumulation of MDSCs in adipose tissue." (PMID 39518420, 2024). "For instance, C-C motif chemokine ligand 2 (CCL2) and C-C motif chemokine ligand 5 (CCL5) are closely associated with obesity-induced cardiovascular disease and insulin resistance." (PMID 39334887, 2024). "Overall, our studies demonstrate that Hdac3 deletion enhances intramembranous bone healing in a setting of diet‐induced obesity, possibly through increased production of CCL2 by macrophages within the defect." (PMID 39261913, 2024). "Elevation of CCL2 in the adipose tissue of patients with obesity attracts monocytes, resulting in inflammation and insulin resistance within the adipose tissue." (PMID 39334887, 2024). "Overnutrition and resultant obesity is involved in the activation of adipose tissue, especially ATMs, leading to higher levels of CCL2." (PMID 39063997, 2024). "The volcano plot also confirmed significant downregulation of various genes in inflammation and obesity including IL-6, IL-1B, CCL2, PPARg, and Fabp4." (PMID 38512816, 2024). "In obesity, the levels of inflammatory mediators increases, and the recruitment of immune cells through chemokine signalling pathways (including CCL2 and CCL5) contributes to the transition of inflammation into a chronic process." (PMID 39275140, 2024). "During obesity, the expression and activity of inflammatory factors are altered, including the up-regulation of CCL2, which leads to more macrophages being recruited into adipose tissue and exacerbate metabolic inflammation." (PMID 39334887, 2024). "CCL-2 is a chemotactic factor, which plays a critical role in monocyte infiltration in central and peripheral tissues in obesity." (PMID 36829858, 2023). "Consistently, in the case of obesity, CCL2 expression is up‐regulated when H3K27Ac enrichment is occupied on the CCL2 promoter of macrophages." (PMID 36872292, 2023). "Strikingly, ob-dT bASCs already displayed an enhanced gene expression of CXCL2, CXCL1, CXCL3, FGF2 and CCL2, compared to ln-dT bASCs, suggesting a crucial impact of obesity on bASCs." (PMID 36710348, 2023). "Nonetheless, the adipose protein profile indicates sex- and RELMα-dependent effects of diet-induced obesity, which correlates with increased proinflammatory CCL2, and decreased anti-inflammatory and Th2 cytokines, IL-10, GM-CSF, and IL-5, respectively." (PMID 37162190, 2023).
Obesity (continued). "The contributory role of the chemokine CCL2/MCP-1 in macrophage recruitment in obesity in metabolic tissues and consequent insulin resistance has been shown early in animal models." (PMID 37509065, 2023). "Two studies discovered that increased levels of chemokine (C-C motif) ligand 2 (CCL2) in AT and plasma is responsible for increased macrophage accumulation in obesity, thus suggesting monocyte recruitment to the AT." (PMID 36994095, 2023). "In obesity, CCL-2 is mainly produced by WAT, and its levels correlate with the degree of WAT accumulation in animals and humans." (PMID 36829858, 2023). "Obesity induces upregulated expression of chemokines such as MCP-1 (monocyte chemoattractant protein-1, CCL2) and CCL5 (C-C Motif Chemokine Ligand 5) in order to recruit M1 macrophages to adipose tissues." (PMID 36838843, 2023). "As CCL2 upregulation in obesity promotes macrophage recruitment into adipose tissue, inhibitors of CCL2 have been developed to reduce TAM within the tumor microenvironment and at sites of metastasis." (PMID 35435599, 2022). "Our data demonstrated a trend toward an increase in obesity-induced Ccl2 expression, which was prevented by SGK1 genetic inhibition (ANOVA P = 0.05)." (PMID 35998035, 2022). "Elevated CCL4 and CCL2 expression levels were reported in obesity and found to be correlated with inflammation and insulin resistance." (PMID 35412419, 2022). "In contrast, there are studies showing a decrease of plasma levels pf CCL2 after exercise interventions in patients having undergone coronary artery bypass surgery, with metabolic syndrome or suffering from obesity." (PMID 36011581, 2022). "Gal-3 blockage decreased obesity-induced cardiac dysfunction, inflammatory markers osteopontin, and CCL2, and fibrosis markers' collagen type I, TGF-β, and connective tissue growth factor." (PMID 35557520, 2022). "In HFD-fed obesity, CCL2 expression increased, followed by large recruitment of ATMs and increased pro-inflammatory cytokines; furthermore, the phenotype switch of ATM toward M1 depended on the expression of CCL2." (PMID 35885044, 2022). "CCL2 is highly expressed in the AT in obesity and the release of MCP-1 from adipocytes constitutes a key signal for monocyte influx." (PMID 36297056, 2022). "Initially, Obesity-induced adipocyte death and adipose tissue inflammation promote a secretion of CCL2 and other chemokines, which bind to their receptors on monocytes circulating in the blood." (PMID 36119080, 2022). "Afterward, based on TFEA and qRT-PCR verification, we confirmed that SOCS3, ICAM-1, NT5E, MYC, CCL2, and PPARG were potential ORDEGs that linked obesity and OLF pathogenesis." (PMID 35712246, 2022). "On the contrary, the inflammatory genes IL‐1β and IL‐8 and monocyte chemoattractant protein 1 (MCP‐1, aka CCL2) were upregulated in ADMSCs acquired from individuals with obesity." (PMID 34985174, 2022). "Obesity also alters the tumor microenvironment to favor an increase in MDSCs by elevating local CCL2 production in HFD-fed mice." (PMID 36430701, 2022). "As adipocyte CCL2 secretion is increased in obesity and promotes WAT inflammation in both humans and animal models, we focused our subsequent analyses on this chemokine." (PMID 35165448, 2022). "Previous study demonstrated that 10% (v/v) plasma from diet-induced obesity (DIO) mice induced higher expression of both CCL2 and IL-6 mRNA than plasma from lean mice in SVFs from DIO mice, but did not have this effect on SVFs from lean mice." (PMID 35883204, 2022). "In this review, we summarized recent data on the importance of C-C motif chemokine ligand 2 (CCL2) in the context of obesity." (PMID 33540898, 2021). "We examined adipose tissue inflammation and focused on CCL2 production because of its critical role in the accumulation of adipose tissue macrophages in obesity and its potential impact on insulin resistance." (PMID 33888702, 2021).
Obesity (continued). "As results, molecular docking findings indicated the binding capability of metformin with key proteins, including interleukin 6 (IL-6) and chemokine (C-C motif) Ligand 2 (CCL2) expressed in obesity- and hypertension-dependent tissues." (PMID 34334083, 2021). "This was consistent with the increased CCL2 expression in obesity and associated with an increase in p65 occupancy at the κB sites located near the TSS of CCL2 in obese OAPs." (PMID 33888702, 2021). "In the process of obesity progression, adipocytes can recruit and activate macrophages through CCL2/IL-1β/CXCL12 signaling pathway." (PMID 34485124, 2021). "In this review, we aimed to summarize and discuss the current knowledge on CCL2 with a focus on its role in linking obesity to cardio-metabolic diseases." (PMID 33540898, 2021). "CCL2 / MCP-1 is elevated in obesity and contributes to insulin resistance, hepatic steatosis, and macrophage accumulation in adipose tissue." (PMID 34154608, 2021). "Using PDB database, IL-6 and CCL2 proteins in obesity and hypertension were screened out, and then 1ALU in IL-6 was selected for docking with metformin biologically." (PMID 34334083, 2021). "Taken with current bioinformatic findings, the key therapeutic targets of IL-6, CCL2 in metformin treating obesity/hypertension were identified through molecular docking validation." (PMID 34334083, 2021). "The initial event in obesity-induced systemic inflammation is the secretion of specific chemokines such as C-C motif chemokine ligand 2 (CCL2) and leukotriene B4 (LTB4) from adipocytes which promote monocyte trafficking into the adipose tissue." (PMID 34671656, 2021). "Taken together, these data suggest a repressive role of BMAL1 on CCL2 transcription in OAPs, which is altered in obesity." (PMID 33888702, 2021). "Increased CCL2 production is observed in, inter alia, patients with excessive body weight and obesity." (PMID 34768469, 2021). "Inflammatory proteins, especially Ccl2 (encoding MCP-1), recruit macrophages into obese adipose tissue and TNF-α further activates the inflammatory cascade, maintaining obesity-induced systemic inflammation." (PMID 34135978, 2021). "The chemokine CCL2 is involved in the pathogenesis of many different diseases, including obesity, atherosclerosis, autoimmune diseases, and many neurological diseases." (PMID 34511129, 2021). "CCL2 is one of the critical chemokines that play a vital role in the development and progression of obesity-related metabolic disease via the inflammatory pathway." (PMID 31964990, 2020). "Obesity has been shown to induce Ccl2 expression in mouse mammary glands for promoting macrophage recruitment and angiogenesis, suggesting that Ccl2 is a pro-tumorigenic, invasive factor for breast cancer." (PMID 32785175, 2020). "In the same study, overexpression of lamin A/C in mouse macrophages revealed chronic inflammation by upregulation of mediators like IL6, TNFα and CCL2 and the development of obesity-induced insulin resistance." (PMID 32872320, 2020). "The elevated CCL2 levels in adipose tissue and blood were also observed in humans during obesity, and in high-fat diet-induced or genetically obese rodents." (PMID 32471499, 2020). "IL1β, IL6, IL10, TNF, interferon gamma (IFNγ) and monocyte chemoattractant protein 1 (MCP1/CCL2), and obesity-associated maternal cytokines likely access the fetus via the placenta." (PMID 33158303, 2020). "It is noteworthy that some of the key molecular players involved in obesity were also strikingly critical in cancer progression, such as NF-κB, CCL2/CCR2, JNK, and HIF/VEGF." (PMID 32471061, 2020). "Under conditions of obesity, adipocytes increase CCL2 expression, leading to elevated recruitment of inflammatory macrophages." (PMID 32731354, 2020). "Chemokine (C-C Motif) Ligand 2 (CCL2) is one of the critical chemokines that play a vital role in the development of obesity-related metabolic disease." (PMID 31964990, 2020).
Obesity (continued). "LPS stimulation increased both the expression of the pro-inflammatory cytokine IL-6 as well as the obesity-induced chemokine, C–C Motif Chemokine Ligand 2 (CCL2)." (PMID 33273595, 2020). "Indeed, our study showed that overexpression of CCL2 in mice is associated with increased liver and decreased muscle weights, which largely mimics a phenotype frequently found in some human metabolic diseases, such as obesity, chronic liver disease or metabolic syndrome, and in aging." (PMID 32686726, 2020). "Since elevated CCL2 in circulation is also one of the typical features of obesity, this supports the role of CCL2 in connection of obesity and cancer promotion." (PMID 32471499, 2020). "Mechanistically, obesity induces a pro-inflammatory microenvironment featured by elevated CCL-2 and IL-6 levels, and promotes the proliferation and activation of encephalitogenic T cells into the CNS." (PMID 31507583, 2019). "It has been recently reported that CCL2 and CCL5 are linked to the obesity-associated infiltration by monocytes/macrophages of adipose tissues." (PMID 31817755, 2019). "We investigated the therapeutic effects and the mechanism of CCL2/CCR2 signaling in obesity-induced kidney injury." (PMID 31498850, 2019). "Activated stress pathways found in obesity drive the expression of chemokines like C-C motif chemokine ligand 2 (CCL2), CCL8, and CCL5, and chemokine receptors (e.g. CCR2 and CCR5), which help recruit macrophages to the dysfunctional tissue." (PMID 32133436, 2019). "Although the secretion of the chemokines KC/CXCL1 and MCP-1/CCL2 remained unchanged in 3T3-L1, our results show that leptin's actions on adipocytes contribute to the inflammatory profile characteristic of obesity." (PMID 31920961, 2019). "We observed enhanced IL-6 and CCL-2 production in obesity animals, which derived from adipose tissue M1 macrophages and adipocytes." (PMID 31507583, 2019). "Obesity is a state of chronic low-grade systemic inflammation which induces the production of several chemokines including CCL2, CCL5, and CXCL5." (PMID 31817755, 2019). "Taken together, these data suggest that obesity promotes the pathogenesis of EAE through CCL-2 and IL-6 mediated CNS inflammation." (PMID 31507583, 2019). "Taken together, these results suggest that IL-6 and CCL-2 are the inflammatory mediators linking obesity with enhanced effector Th responses and EAE." (PMID 31507583, 2019). "Higher levels of some adipocytokines (TNF, CCL2/MCP-1) in ScAT from OA than RA patients can also result from different body compositions, as obesity was more frequent in OA than RA group." (PMID 30280295, 2019). "Macrophages are recruited to adipose tissue in part via CCR2 interaction with CCL2 that is upregulated in obesity." (PMID 30254630, 2018). "Analysis restricted to adipocytes, the main source of circulating miRNAs in obesity, identified 3 mRNAs (CCL2, STEAP2, EN1) as the main target of miR-374a-5p." (PMID 29769661, 2018). "CCL2 upregulated in hepatocytes and hepatic stellate cells mediates obesity-induced hepatic inflammation." (PMID 29915246, 2018). "We will mainly focus on CCL2/MCP-1, as it is the major chemokine active in macrophage recruitment and also responsible for adipose tissue inflammation in obesity, where the size of adipocytes correlates with MCP-1 levels." (PMID 29599894, 2018). "In obesity, adipocytes can release proinflammatory mediator like CC chemokine ligand (CCL)-2, and monocyte chemoattractant molecule (MCP)-1, which induce the recruitment of ATMs47." (PMID 29109438, 2017). "Plasma CCL2 levels in ob/ob mice have been reported to be unaffected by obesity per se, but increased after stroke." (PMID 28798136, 2017). "At 16wk of HFD-feeding, expressions of the pro-inflammatory cytokines Ccl2 and TNFα, as well as the macrophage marker F4/80 were most profoundly elevated in gWAT, suggesting that clock gene damping within this tissue may be linked to the development of obesity-related inflammation." (PMID 27439882, 2016).